CYP1B1 (cytochrome P450 family 1 subfamily B member 1)
Diseases named in the same sentence as CYP1B1 in open-access papers (continued):
Sharing a sentence is not in itself a finding about the gene and the disease.
Oral leukoplakia (1 paper, 2018). A thickened white patch on the oral mucosa that cannot be rubbed off. "Xenobiotic metabolizing enzymes CYP1A1 and CYP1B1 were observed also in a cellular model of oral leukoplakia." (PMID 30041465, 2018).
ovarian dysfunction (1 paper, 2025). The inability of the ovaries to function. "Therefore, decreasing Cyp1b1 activity may be a therapeutic strategy for ovarian dysfunction." (PMID 40704148, 2025).
pemphigus (1 paper, 2021). Pemphigus is a group of rare autoimmune diseases that cause blistering of the skin and mucous membranes (mouth, nose, throat, eyes, and genitals).This conditioncan occur at any age, but often strikes people in middle or older age. "Analysis of neuroendocrine genes revealed that ADRB1, MCR5, and CYP1B1 were significantly downregulated in pemphigus vs. healthy controls." (PMID 34660634, 2021). "We found that genes enriched in localized human pemphigus foliaceous compared to pemphigus vulgaris, including CCL5 and CYP1B1 were also captured in the canine DEGs when examined by two-tailed student's t-tests." (PMID 34660634, 2021).
periodontitis (1 paper, 2023). An acute or chronic inflammatory process that affects the tissues that surround and support the teeth. "In the present study, AhR and its direct targets CYP1A1 and CYP1B1 were reduced in P. gingivalis‐infected experimental periodontitis mice model." (PMID 36446468, 2023). "Similarly, gene expression of AhR, CYP1A1, CYP1B1, and IDO analysed by qRT‐PCR were also decreased in periodontitis mice." (PMID 36446468, 2023).
postmenopausal osteoporosis (1 paper, 2025). Metabolic disorder associated with fractures of the femoral neck, vertebrae, and distal forearm. "Moreover, polymorphisms in estrogen metabolism-related genes, such as PDSS1, CYP19A1, CYP1A1, and CYP1B1, have been associated with varied efficacy of raloxifene, a selective estrogen receptor modulator frequently prescribed for postmenopausal osteoporosis." (PMID 40411668, 2025).
prostate adenocarcinoma (1 paper, 2022). "To further examine the effect of CYP1B1 on PCa progression, we analyzed CYP1B1High (n = 50) and CYP1B1Low (n = 50) available prostate adenocarcinoma (PRAD) samples in the TCGA dataset." (PMID 35292057, 2022). "CYP1B1High prostate adenocarcinoma patients displayed higher IL6 levels than CYP1B1Low prostate adenocarcinoma patients, and coexpression of CYP1B1 and IL6 was found in PCa tissues and PCa cell lines." (PMID 35292057, 2022).
pulmonary fibrosis (1 paper, 2023). Chronic progressive interstitial lung disorder characterized by the replacement of the lung tissue by connective tissue, leading to progressive dyspnea, respiratory failure, or right heart failure. "Genetic polymorphisms in SNPs related to ROS metabolism, such as cytochrome P450 Family 1 subfamily A Member 1 (CYP1A1) and cytochrome P450 Family 1 subfamily B Member 1 (CYP1B1), as well as antioxidant enzymes, such as GST and SOD, increase susceptibility to CS-induced pulmonary fibrosis." (PMID 37371940, 2023).
rectal cancer (1 paper, 2022). A primary or metastatic malignant neoplasm that affects the rectum. "In our study, CYP1B1, ANO1, and RIOK3 were negatively associated with prognosis and nCRT response in rectal cancer." (PMID 36505493, 2022).
retinal ischemia (1 paper, 2020). A ischemic disease that involves the retina. "We recently showed retinal AC constitutively express Cyp1b1, and global Cyp1b1-deficiency (Cyp1b1-/-) attenuates retinal ischemia-mediated neovascularization in vivo and the pro-angiogenic activity of retinal vascular cells in vitro." (PMID 32330152, 2020).
schizophrenia (1 paper, 2025). A major psychotic disorder characterized by abnormalities in the perception or expression of reality. "In summary, an inverse connection between CYP1A1 and miR-21; CYP1B1 with miR-27b and miR-200c; and CYP1A2 with miR-122 points to a miRNA-CYP enzyme regulatory network in schizophrenia that can be readily detected in the blood." (PMID 39812050, 2025). "Additionally, miR-27b, miR-200c, miR-21 and miR-122 and miR-132 may serve as ideal theranoMiRNAs in schizophrenia, particularly when analysed in conjunction with CYP1A2, CYP1B1 and CYP1A1 activities." (PMID 39812050, 2025).
steatosis (1 paper, 2018). Increased lipid within the cytoplasm of cells. "Regarding more specifically B[a]P metabolism, it is worth noting that neither CYP1A1 nor CYP1B1 mRNA expressions were affected by steatosis alone, in contrast to CYP1A2 whose expression was reduced." (PMID 29654281, 2018).
tuberculosis (1 paper, 2025). A chronic, recurrent infection caused by the bacterium Mycobacterium tuberculosis. "In TB-T2DM comorbidity, CYP1B1-induced lipid metabolism dysregulation may impair the ability of macrophages to clear M. tuberculosis, creating a vicious cycle of inflammation and metabolic abnormalities." (PMID 40917351, 2025).
uterine cancer (1 paper, 2025). Primary or metastatic malignant neoplasm involving the uterine corpus and/or the cervix. "CYP1B1 has been shown to play an important regulatory role in estrogen-related malignant tumors, such as breast, ovarian, and uterine cancers." (PMID 40989158, 2025).
vascular ectasia (1 paper, 2018). "For example, nodes such as CYP1A1, CYP1A2, CYP1B1 in module 1 belonged to cytochrome P450 (CYPs) family, which could enrich in epoxygenase P450 pathway and relate with cardiovascular-related functions such as vascular ectasia." (PMID 30158870, 2018).
vitamin A deficiency (1 paper, 2020). Deficiency of vitamin A due to malnutrition, malabsorption, or dietary lack. "A functional link between Cyp1b1 and dietary retinol has been discovered from shared perinatal effects on hepatic gene regulation provided by gestational vitamin A deficiency (GVAD) and Cyp1b1 deletion." (PMID 32027669, 2020).
vitiligo (1 paper, 2020). Generalized well circumscribed patches of leukoderma that are generally distributed over symmetric body locations and is due to autoimmune destruction of melanocytes. "The neuroendocrine gene CYP1B1 was significantly downregulated in cases versus controls, though this contrasts with a previous report describing upregulation in vitiligo blood samples." (PMID 33384688, 2020).
cancer (187 papers, 2001 to 2025). A tumor composed of atypical neoplastic, often pleomorphic cells that invade other tissues. "IHC analysis of 80 TNBC samples confirmed an association between elevated tumor cell CYP1B1 and residual cancer burden class 2/3 disease after NAC in T cell–excluded (TCE) TNBC (P < 0.01) but not in T cell–infiltrated (TCI) TNBC." (PMID 40478625, 2025). "CYP1B1 was significantly associated with estrogen signaling and tryptophan metabolism, indicating its role in hormone‐driven cancer and metabolic reprogramming." (PMID 40817807, 2025). "The associations of CYP1B1 R48G (142C > C) and ERα 975C > G polymorphisms with EC cancer risk have been identified in the Polish subpopulation of Caucasians." (PMID 39682707, 2024). "Induction of CYP1A1 and CYP1B1 is specifically associated with metabolizing BAP to ultimately produce a diol-epoxide which can lead to the development of cancer." (PMID 38706568, 2024). "Both ABCB1 and CYP1B1 exhibit associations with microRNAs in cancer and the Nuclear Receptors Meta-Pathway (WP2882)." (PMID 38534761, 2024). "A case–control study of the associations between the CYP1B1 and COMT polymorphisms and invasive EC risk revealed that carriers of the CYP1B1 N453S allele had a statistically significant decrease in cancer risk." (PMID 39682707, 2024). "CYP1B1 is a critical metabolic enzyme for melatonin metabolism, and its role in cancer has been emphasised; this suggests that dysregulated expression of CYP1B1 is associated with the tumour’s clinical stage, grade, survival, and immune microenvironment." (PMID 39457550, 2024). "This study delves into the expression of drug resistance-associated genes, ABCB1 and CYP1B1, in cancer cells." (PMID 38534761, 2024). "A meta-analysis conducted on various cancer types has shown that the A119S polymorphism in the CYP1B1 gene is associated with PCa risk among Caucasians." (PMID 39682707, 2024). "The CYP1B1 gene is a gene encoding an enzyme that is involved in processes such as cancer cell metastasis, invasion, and drug resistance, and is associated with oxidative stress." (PMID 37854320, 2023). "CYP1B1 was involved in the infiltration of the lymphocyte, immunomodulator, chemokine, receptor, and cancer associated fibroblast (CAF) in cancer." (PMID 36428734, 2022). "Accumulated evidence has revealed that the single nucleotide polymorphism of CYP1B1 is associated with the risk of cancer, including prostate, endometrial, and ovarian cancer." (PMID 36428734, 2022). "The capacity of cancer associated AhR/CYP1B1, P2Y1r and mGluR5 to upregulate the NAS/melatonin ratio is important." (PMID 36613754, 2022). "Several studies have comprehensively and quantitatively analyzed the role of CYP1B1 polymorphisms in the increased risk and development of cancer." (PMID 34636736, 2021). "These CYP1B1 polymorphisms are believed to increase cancer risk through molecular mechanisms such as enhanced progesterone and estrogen receptor signaling, which is also known to affect chemotherapy response." (PMID 34636736, 2021). "CYP1B1 4326 C>G polymorphism has been implicated in contributing to the differences in treatment response in various types of cancers." (PMID 33906328, 2021). "Abundant evidence shows that CYP1B1 expression is associated with aggressive behavior and poor survival in several cancers." (PMID 34636736, 2021). "In conclusion, we have demonstrated for the first time the crucial importance of a frequent CYP1B1 polymorphism for cancer cell proliferation, migration and resistance to chemotherapy, both in vitro and in vivo." (PMID 32565541, 2020). "The association between CYP1B1 polymorphisms and increased cancer risk has been extensively studied." (PMID 33185690, 2020). "Single-nucleotide polymorphisms (SNPs) associated with CYP1B1 have been reported to a possible biomarker for therapy response in cancer." (PMID 32947941, 2020).
cancer (continued). "The mechanisms by which CYP1B1 polymorphisms increase cancer risk include enhanced estrogen and progesterone receptor signaling, also known to influence cancer treatment response." (PMID 33185690, 2020). "Increased cytokine interleukin-6 and leptin lead to elevated CYP1B1 activity, which possibly causes cancer." (PMID 32626511, 2020). "CYP1B1 overexpression results in the conversion of estrogens to quinone forms, which bind with DNA and create a predisposition for cancer in several organs, such as the brain, breast, and ovary." (PMID 32626511, 2020). "CYP1B1 overexpression has been associated with the increase in cancer risk via pro-inflammatory cytokines, metastasis, and disturbance in the regulation of cell proliferation, migration, and differentiation." (PMID 33185690, 2020). "Interaction between smoking and CYP1B1 polymorphisms leading to cancer has been shown in other studies." (PMID 30133114, 2018). "Studies are required to confirm the validity of this SNP in other ethnic populations, and the mechanism of CYP1B1 genetic polymorphism affecting cancer progress should be explored in vitro and in vivo." (PMID 28377924, 2017). "Over the last two decades, a number of case-control studies were conducted to investigate the association between CYP1B1 gene polymorphism and cancer risk in humans." (PMID 28377924, 2017). "The occurring and development of cancer are associated with abnormity of multiple cancer-related genes, among which CYP1B1 acts as an important phase I metabolism enzyme participating in regulating the metabolic activation." (PMID 28377924, 2017). "Since CYP1B1 is implicated as an important factor in the development of various cancers, understanding the precise mechanisms of CYP1B1-mediated cancer progression is required in the development of new strategies for cancer treatment." (PMID 28388569, 2017). "In summary, to the best of our knowledge, our present study is the first report to identify the molecular mechanism underlying CYP1B1-mediated cancer progression." (PMID 26981862, 2016). "CYP1B1 is a tumor-associated protein, which has been shown to be overexpressed in various malignant tumors." (PMID 26580399, 2015). "In conclusion, this meta-analysis suggests that the CYP1B1 L432V polymorphism is associated with urinary cancer development, especially in specified Caucasian and Asian populations." (PMID 24913727, 2014). "Cytochrome P450 1B1 (CYP1B1) is a universal cancer marker and is implicated in many other disorders." (PMID 25329831, 2014). "Although many polymorphisms of the CYP1B1 gene have been associated with different cancers, less is known about changes in mRNA expression levels in tumor tissue." (PMID 24151610, 2013). "We genotyped 597 cancer patients and 597controls for three CYP1B1 SNPs, which have previously been shown to be associated with altered enzymatic activity." (PMID 20701755, 2010). "In summary, the CYP1B1 variants examined in this study suggest that they contribute to inter-individual differences in cancer risk and are potentially valuable in genetic risk assessment." (PMID 20701755, 2010). "Several studies have examined the relationship between individual CYP1B1 polymorphisms and cancer risk." (PMID 20701755, 2010). "The studies between genetic polymorphisms in the CYP1B1 gene and risk to a variety of cancers have focused on amino acid substitutions in exon 3, namely L432V and N453S." (PMID 14562027, 2003). "The association between the polymorphisms of CYP1B1, especially L432V, and susceptibility to several cancers has been investigated." (PMID 14562027, 2003). "Overexpression of CYP1B1 in tumors has been linked to resistance to certain chemotherapeutic drugs, partly because CYP1B1 can metabolize (and thus inactivate) these drugs or otherwise enhance survival pathways in cancer cells." (PMID 40883330, 2025). "Previous studies have linked CYP1B1 to the progression of various cancers." (PMID 38184608, 2024).
cancer (continued). "Studies examining the rs1800440 CYP1B1 polymorphism and cancer risk have been inconclusive." (PMID 37783717, 2023). "Interestingly, the top upregulated gene in cluster 1 was CYP1B1, which has been found to be associated with cancer development." (PMID 35664743, 2022). "The associations of CYP1B1 expression on immune and molecular subtypes in cancers was investigated." (PMID 36428734, 2022). "Besides PCG, CYP1B1 has also been linked with other diseases, including various types of cancer and cardiovascular diseases." (PMID 36518267, 2022). "We have an interest in the cancer-associated CYP named CYP1B1." (PMID 35752630, 2022). "Immunological correlation analysis showed CYP1B1 was positively correlated with the infiltration of lymphocyte, immunomodulator, chemokine, receptor, and cancer-associated fibroblasts (CAFs) in most cancer." (PMID 36428734, 2022). "In an era of precision medicine, cancers with high-activity CYP1B1 variants may better respond to the beneficial effects of CYP1B1 inhibitors." (PMID 33185690, 2020). "A more detailed understanding of the underlining mechanisms of CYP1B1-mediated carcinogenesis may help in the development of new methods for cancer treatment." (PMID 32626511, 2020). "Therefore, inhibitors of CYP1B1 are poised to optimize the benefit and reduce the cardiovascular risk of cancer treatments by interfering with these divergent signaling pathways." (PMID 33185690, 2020). "In addition, recent studies have found a link between CYP1B1 polymorphisms and a reduced or enhanced risk of certain types of cancers." (PMID 31998435, 2020). "This was especially significant for the subgroup of metastatic patients, which showed that the V432L polymorphism of CYP1B1 may interfere with fundamental features of cancer cell fate orientation." (PMID 32565541, 2020). "Despite the association between CYP1B1 and cancer, the detailed molecular mechanism is still unknown." (PMID 35515562, 2019). "Similarly, the association of CYP1B1 polymorphisms and the risk of several types of cancer has been explored." (PMID 30765615, 2019). "Thus, data from our study and other studies have consistently shown that the CYP1B1*2 G355T allele is linked to cancer susceptibility." (PMID 25299224, 2014). "Further biological investigations may eventually lead to better understanding of the association between the CYP1B1 polymorphism and urinary cancer risk." (PMID 24913727, 2014). "It is entirely possible that the discrepancies found among these results concerning the effect of mutation allele CYP1B1 4326G on cancer risk might derive from the different ethnicities, subject numbers, and additional SNPs included in the studies." (PMID 25299224, 2014). "This depends on what pro-carcinogens are the frequent cancer-causing agents in these tissue types and whether CYP1B1 serves to activate or inactive them." (PMID 24151610, 2013). "However, future studies are needed to elucidate the role of CYP1B1 polymorphism and contaminant interaction and the risk of hormone mediated cancers." (PMID 23785672, 2013). "Two of the CYP1B1 SNPs we assessed have previously been linked to cancer." (PMID 23637977, 2013). "Previous studies showed that CYP1B1 polymorphisms may be involved in cancer risk, alone or in combination with other factors." (PMID 20875115, 2010). "Therefore, in the present study we evaluated functional polymorphisms of CYP1B1, which play an important role in cancer risk and progression as well as in the metabolism of cancers modulated by sex hormones." (PMID 20875115, 2010). "However, few studies have thoroughly investigated the association of multiple SNPs in CYP1B1 and cancer risk." (PMID 14562027, 2003). "If PAs inhibit CYP1B1 activity, they may reduce the formation of DNA-reactive estrogen metabolites and limit the activation of environmental procarcinogens, thereby lowering the risk of cancer initiation and progression." (PMID 40883330, 2025).